AGO1 (argonaute RISC component 1)
Diseases named in the same sentence as AGO1 in open-access papers (continued):
Sharing a sentence is not in itself a finding about the gene and the disease.
infection (continued). "Whereas AGO1 had transcript levels nearly as high as the housekeeping gene WS41, AGO3 exhibited much lower levels, and in fact transcripts could not be detected at the 3 hours post infection (hpi) or 6 hpi treatments." (PMID 30555430, 2018).
cancer (40 papers, 2010 to 2025). A tumor composed of atypical neoplastic, often pleomorphic cells that invade other tissues. "AGO1 mutants were positively associated with late-stage (III/IV) in HNSC cancers (p = 0.015) and a worse outcome in BRCA (DFS, p = 0.030, PFI, p = 0.011)." (PMID 36672288, 2023). "The most striking results were achieved for the AGO1 rs636832 GA genetic variant, which was found to hold a protective effect on overall cancer risk." (PMID 33668654, 2021). "A series of case vs. control studies implicated the possible application of AGO1 genotyping in cancer risk assessment." (PMID 33668654, 2021). "This understanding of the new role of Ago-1 unravels the pathway dictating the principle and cause for various diseases including cancer and neuro degenerative diseases." (PMID 29385168, 2018). "We found 17 genes with hypomethylation or copy number gain and increased expression, including cancer-associated genes such as AGO1, GHR and FAT1, which might be potential oncogenes." (PMID 37245006, 2023). "Moreover, another of the analyzed AGO1 SNPs variant, rs595961 AG, was implicated as a cancer risk factor for the Asian population." (PMID 33668654, 2021). "In the context of cancer, it is important to determine whether AGO1 loss of function alters MYC-dependent cancer progression and vice versa." (PMID 32527935, 2020). "In addition, AGO1 is significantly associated with oncogene promoters in cancer cells and affects Pol II recruitment." (PMID 30356106, 2018). "The discrepancy between the inferred interactions from our pipeline and the CLASH-reported interactions may be explained by the fact that the former reported conditional interactions highly associated with cancers while the latter reported interactions associated with AGO1 protein in HEK293 cell." (PMID 29042600, 2017). "We provide evidence that a cancer-associated SNP influences this paRNA-based regulatory network by modifying the secondary structure of the sense transcript within the miRNA/AGO1 binding region, thereby increasing the accessibility of the miRNA/AGO1 complex to the paRNA and the CDH1 promoter." (PMID 28555645, 2017). "It has recently been shown that Ago1 binds to the promoter of actively transcribed genes in human cancer cells like a bona fide transcription factor." (PMID 38781128, 2024). "On the other hand, a human AGO1 promotes gene expression in human cancer cells by interacting with RNA polymerase II." (PMID 35081172, 2022). "Although small RNA functions and their potential application in neoplasia has been greatly explored in the last 20 years, the studies on their partner proteins, AGO1–4, and the involvement in cancer development has largely lagged behind." (PMID 33668654, 2021). "Understanding of AGO1–4 involvement in tumorigenesis will most probably be followed by the clinical application of the knowledge to aid the development of RNAi-based anti-cancer strategies." (PMID 33668654, 2021). "The dysregulated expression of the genes encoding AGO proteins, with emphasis on AGO2 and, to a lesser extent AGO1, was demonstrated in neoplastic tissues of numerous cancer types." (PMID 33668654, 2021). "The second network contained 6 of the identified autoantigens (AGO1, CSNK1G1, IFIT5, PHC3, SRP19, and UBE2S) out of the 35 molecules associated with cancer, organismal injury and abnormalities." (PMID 31494269, 2019). "An additional interesting observation from our network analysis is that the AGO1 transcript is significantly overtargeted by the larger number of cancer-correlated miRNAs (AGO1 is targeted by four out of the top 10 Green module miRNAs)." (PMID 31616639, 2019). "We demonstrate that subtle changes in the expression of Ago-1 lead to chronic effect on gene regulation that promotes different diseases including cancer." (PMID 29385168, 2018). "Another study found that human Ago1 bound directly to RNA polymerase II and the promoters of actively transcribed genes in cancer cells." (PMID 29267401, 2017).
cancer (continued). "Speaking of potential model applications in the context of disease pathology, since the prominence of AGO1 and let-7 profiles in cancer has already been validated, the next step is to connect our model with miR features in vascular disease." (PMID 26588727, 2015). "In support, integrated analysis of ChIP-seq and gene expression profiling places Ago1 in various major cancer-related signaling pathways involved in regulating DNA damage response, mitogenic signaling, cell cycle, angiogenesis, and apoptosis." (PMID 24086155, 2013). "Analysis of Ago1 protein levels in non-tumorigenic (RWPE-1 and PWR-1E) and cancerous (PC-3, DU145, LNCaP, RV1, CWR22R, and C4-2) prostate cell lines indicated Ago1 is generally expressed at significantly higher levels in cancer cell lines." (PMID 24086155, 2013). "In the present study, we investigate the nuclear functions of Ago1 and Ago2 – the major facilitators of miRNA activity – from a global prospective using human cancer cells as a model system." (PMID 24086155, 2013). "Strikingly, the genes bound and regulated by Ago1 are mostly genes that stimulate cell growth and survival, and are known to be involved in the development of cancer." (PMID 24086155, 2013). "In the present study, we reveal another layer to Ago1 in regulating gene expression within the nucleus of human cancer cells." (PMID 24086155, 2013). "Further investigation into AGO1, TNRC6B, NOVA1, MMP16, and their connection to miRNA processing could provide deeper insights into the molecular mechanisms underlying cancer recurrence." (PMID 39070144, 2024). "Previous studies have shown that ATM and AGO1 promote the progression of different types of cancer." (PMID 38478802, 2024). "These processes can interact with Ago1 and positively affect gene expression in cancer cells." (PMID 38534453, 2024). "The SNP variations of GEMIN4 and AGO1 have been found to influence different types of cancer." (PMID 36551880, 2022). "Moreover, AGO1-mediated transcriptional activation of cancer related genes, in a manner dependent on AT repeats at the promoter region, was implicated in neoplasia of various origin." (PMID 33668654, 2021). "In human cancer cells, the involvement of AGO1 in chromatin remodeling has been reported." (PMID 33668654, 2021). "Several investigations have reported that AGO1 played a role in various cancers." (PMID 33414440, 2021). "In addition, hsa-mir-106b-5p also targets genes that play an important role in immunity such as APP, VEGFA, KAT2B, MAPK8, and AGO1 and this miR-mRNA binding allows post-transcription disruption of these genes to influence cancer development." (PMID 33773548, 2021). "Target selection for miR-100 was more challenging as there are far less validated targets and even less related to cancer progression, thus we analyzed the validated survival related target mammalian target of rapamycin (mTOR), as well as Ago1 and Ago2 which are predicted targets of miR-100." (PMID 32872485, 2020). "We also noticed in the network of Green module-overtargeted genes that AGO1 was the transcript overtargeted by the larger number of cancer-correlated miRNAs, which suggest a central, hub-like role for this gene in mediating the network effects of the Green module." (PMID 31616639, 2019). "In summary, our results contribute to a better mechanistic understanding of the role of AGO2 in transcription regulation and may inform future avenues of research with respect to AGO1 and control of cancer progression." (PMID 30356106, 2018). "As a consequence, AGO1 depletion reduces proliferation of tumorigenic cell lines, indicating that AGO1 may serve as a useful therapeutic target in treatment of cancers." (PMID 30356106, 2018). "The relationship between AGO1 and cancer has been reported in several recent investigations." (PMID 29487329, 2018).
cancer (continued). "Though AGO1 could not lead apparent expression change of p21 gene in the process of RNAa, AGO1 may have something to do with the control of constitutive and alternative splicing in human cancer cells." (PMID 27639690, 2016). "Boominathan reported that TA-p73 may regulate the post-transcriptional processing of miR-134 by increasing Ago1/2 activity, thereby repressing cancer stem cell proliferation." (PMID 24498348, 2014). "Our findings reveal the first landscape of human Ago1-chromosomal interactions, which may play a role in the oncogenic transcriptional program of cancer cells." (PMID 24086155, 2013). "The findings from our study unveil an unexpected role of nuclear Ago1 in regulating gene expression which may be important both in normal cellular processes and in disease such as cancer." (PMID 24086155, 2013). "In PC-3 cells, Ago1 appeared to preferably drive the expression of genes involved in oncogenic pathways suggesting it may play a role in the cancer phenotype." (PMID 24086155, 2013). "Inhibition of AGO1 could reduce cancer cell progress and survival." (PMID 29487329, 2018). "We observed that AGO1/2, EIF4A3, ELAVL1, and PTBP1 were the main RBPs acting in most of the cancer-related and gene regulation enriched pathways." (PMID 35805051, 2022). "Given the impact of the presented advances in the delineation of AGO1 and AGO2 dysregulation and activity in cancers of various origin, the broad function of the AGOs in neoplastic transformation will be further documented in the foreseeable future." (PMID 33668654, 2021). "In this study, by taking a genome-wide approach, we found that human Ago1, but not Ago2, is pervasively associated with gene regulatory sequences known as promoter and interacts with the core component of the gene transcription machinery to exert positive impact on gene expression in cancer cells." (PMID 24086155, 2013). "Similar results were also observed in AGO1, RPS27A, SP1, and ETS2 of several cancers." (PMID 35911954, 2022). "miR-103a is shown to promote cancer-like properties by down-regulating KLF-4 and DAPK, but has also an interesting role in the modulation of miRNA processing and function via down-regulation of Dicer and miRNA binding Argonaute AGO1." (PMID 25822230, 2015). "Our data represents the first landscape of Ago1-chromosomal interactions in human cancer cells, while revealing a novel non-canonical function for Ago1 in regulating gene expression." (PMID 24086155, 2013). "Therefore, dual role of AGO1 in cancers could not be excluded and further study is necessary." (PMID 29487329, 2018).
tumor (36 papers, 2007 to 2026). "First, tumor cell lines available in the lab were tested using RT-qPCR in order to identify those that express one or the other AGO1 mRNA variant." (PMID 39051182, 2024). "AGO1 gene mutation was more enriched in T4 compared to T1/2/3 tumor stage (OR = 2.95, 95% CI = 1.52–5.72, p = 0.001) and in stages III/IV compared to stages I/II (OR = 2.34, 95% CI = 1.36–4.0, p = 0.002)." (PMID 36672288, 2023). "Larger tumor size was associated with both AGO1 (OR = 2.54, 1.25–5.18, p = 0.010) and DGCR8 (OR = 2.75, 1.47–5.17, p = 0.002) mutations." (PMID 36672288, 2023). "Another neoplasia, partially facilitated by specific genetic variants of AGO1, is clear cell renal cell carcinoma." (PMID 33668654, 2021). "hMex-3A and 3B are also associated with Argonaute (Ago) proteins (Ago1 and Ago2) which are the key components of the RNA-induced silencing complex and have been implicated in tumor development." (PMID 28977858, 2017). "However, decreased expression of AGO1 (Chi-square test, p = 0.001) and Drosha (Chi-square test, p < 0.001) was associated with advanced pathological tumor stage and with MIBC compared to NMIBC (Fisher’s exact test, p < 0.001)." (PMID 29857476, 2018). "In vitro, AGO1 knockdown in mouse ECs co-cultured with E0771 tumor cells led to higher levels of Cxcl10 and Vcam1 expression, suggesting a pro-inflammatory and leukocyte-recruiting effect." (PMID 42286210, 2026). "During the in silico screening we carried out, the genomic region harboring the AGO1 gene emerged as a potential locus undergoing the process of dual DNA hypo/hypermethylation in tumor cells." (PMID 39051182, 2024). "Consistently, AGO1 mRNA levels were generally low in tumor cell lines with a hypermethylated AGO1 promoter." (PMID 39051182, 2024). "The strong correlation between the mRNA level of PUS10 and that of established microRNA biogenesis-associated proteins, such as DICER, DGCR8, AGO1 and AGO3, in KIRC tumor tissues hinted at the involvement of PUS10 in microRNA processing." (PMID 37596681, 2023). "But if a patient has PSA values > 7.65, and the relative expression of AGO1 is ≤ 6.41, 59.4% of patients can be classified as potentially having an aggressive tumour." (PMID 37978493, 2023). "While AGO1 and DGCR8 mutations conferred around 2.5 times higher risk of advanced tumor size, DROSHA mutations were 2.5 times more likely to present with poorly differentiated tumors at the time of diagnosis." (PMID 36672288, 2023). "Cell lines and xenograft tumours with PVT1 or AGO1 knockdown were used to investigate the effects on cell death and tumour growth." (PMID 34288373, 2021). "Immunoblot assays provided the evidence that the expression of AGO1 in POU2F2-depleted tumor tissues were obvious decrease compared with that in control, consistent with the previous data." (PMID 33832481, 2021). "Specifically, the tumour volume curve and tumour weight of sh‐PVT1 or sh‐AGO1 were significantly decreased compared with those in relative scramble." (PMID 34288373, 2021). "Here, we report novel tumour suppressor activity for the Drosophila Argonaute family RNA-binding protein AGO1, a component of the miRNA-dependent RNA-induced silencing complex (RISC)." (PMID 32527935, 2020). "Some studies have already reported a tumor specific expression of AGO1, AGO2, Dicer and Drosha in the urogenital tract." (PMID 29857476, 2018). "Our findings propose that Ago-1 acts as a key regulator in controlling cell death, tumor regression and stress response in metazoan providing a constructive bridge between RNAi machinery and cell death." (PMID 29385168, 2018). "Other factors influencing the tumor response to TBG-RNAi-CK2 in these two prostate models related to the levels of argonaute 1 (Ago 1), Ago 2, and GW182, which were present in higher amounts in the PC3-LN4 xenograft tumors compared with 22Rv1." (PMID 28230733, 2017).
tumor (continued). "Previously, several researchers have reported the dysregulation and potential role of DICER, GEMIN4 and AGO1 in tumor progression, including GC." (PMID 29156806, 2017). "Interestingly, significant correlations between hypomethylation/activation of AGO1-V2 and hypermethylation/repression of AGO1 were observed upon examination of tumor cell lines and tissue datasets." (PMID 39051182, 2024). "By doing so, we found a significant decrease in the expression of TNRC6B, AGO1, and CDK6 between the low-risk and high-risk groups, pointing to a decrease in the repressive machinery of microRNAs and proliferation in the aggressive tumours." (PMID 37978493, 2023). "PVT1 or AGO1 inhibition is also responsible for the promoted Ki67 level in excised tumour tissue." (PMID 34288373, 2021). "In conclusion, we found that the newly identified miR-153-5p/AGO1 axis was responsible for tumor occurrence and progression via PI3K/Akt signaling, which may therefore provide promising therapeutic targets and prognostic biomarkers for patients with ccRCC." (PMID 33414440, 2021). "In addition, as an important signalling pathway related to the regulatory roles on tumour cell activity, we determined the expression of transforming growth factor‐β (TGF‐β) pathway‐associated proteins in AGO1‐depleted cells." (PMID 34288373, 2021). "Next, we investigated whether the role of miR-153-5p on tumor progression was mediated via downregulation of AGO1." (PMID 33414440, 2021). "Moreover, we initially verified argonaute (AGO) RNA-induced silencing complex (RISC) catalytic component 1 (AGO1) as the direct target of miR-153-5p and the function of AGO1 as a tumor suppressor in ccRCC." (PMID 33414440, 2021). "Moreover, AGO1 depletion resulted in significant inhibition of HCC cell proliferation, which is also associated with tumor progression." (PMID 29487329, 2018). "The alteration of AGO1 expression could influence the functions of HCC tumor cells, including proliferation and invasion." (PMID 29487329, 2018). "AGO1 staining was found in the cytoplasm and partly in the nuclei of normal and tumor tissue." (PMID 29857476, 2018). "The single-stranded RNAi-CK2 oligomer employed by us may be inducing miRNA-like translational repression mechanisms in the tumor cells consistent with the robust expression of Ago1 relative to Ago2 in the xenografts." (PMID 27557516, 2016). "Similarly, AGO1 is also overexpressed along the tumour progression in serous ovarian carcinoma." (PMID 34288373, 2021). "Besides, we observed that AGO1 knockdown significantly promoted tumor proliferation and metastasis." (PMID 33414440, 2021). "Based on the present study in Drosophila it is resolved that, Ago-1 acts as a regulator of cell death, which is crucial for proper development of organs and might act as a tumour suppressor by inhibiting onco-miR-14 expression as well as by promoting JNK-dependent apoptosis." (PMID 29385168, 2018). "Another study found overexpression of AGO1 could reduce tumor growth in animal models." (PMID 29487329, 2018). "As a key component of the RNA-induced silencing complex, Argonaute 1 (AGO1) regulates tumor biology, yet the specific function of AGO1 within ECs in the tumor microenvironment remains undefined." (PMID 42286210, 2026). "Based on these results, it is possible to speculate that miR-145-5p behaves as a tumor suppressor miRNA when it is complexed with Ago2 protein, while miR-145-5p activity may become oncogenic in the absence of Ago2, through the interaction with other RNA-binding proteins (RBPs), as for example Ago1." (PMID 30622242, 2019). "We observed significant over-expression of ADAR, ADARB1, DDX5/17/20, DGCR8, DICER1, DROSHA, EIF2C1-4 (AGO1-4), GEMIN4, POLR2A, TARBP2, TNRC6A and XPO5 in tumor tissue compared to adjacent mucosa." (PMID 31510013, 2019).